S100A10 (S100 calcium binding protein A10)
Diseases named in the same sentence as S100A10 in open-access papers (continued):
Sharing a sentence is not in itself a finding about the gene and the disease.
cancer (continued). "Third, our studies with the S100A10 knockout (null) mouse, obtained from the Svenningsson laboratory, have transformed our understanding of the physiological function of S100A10 and set the stage for our subsequent studies with transgenic mouse models of cancer." (PMID 34944416, 2021). "Lastly, we describe the potential of S100A10 as a biomarker for cancer diagnosis and prognosis." (PMID 34944416, 2021). "Furthermore, S100A10 protein expression (IHC) was observed in primary carcinomas and significantly correlated to poor overall survival (OS), and progression-free survival (PFS), and finally, poor response to chemotherapy in Cox multivariate analysis." (PMID 34944416, 2021). "S100A10 (p11) is a plasminogen receptor that regulates cellular plasmin generation by cancer cells." (PMID 33297495, 2020). "S100A10 is essential for cancer cell invasion and migration." (PMID 30394687, 2019). "Notably, CPT1A functions as a succinyltransferase by binding to S100A10 and promoting its succinylation, which enhances cancer metastasis and invasion." (PMID 30394687, 2019). "S100A10 mRNA levels were significantly lower in normal tissues than in cancer tissues." (PMID 30394687, 2019). "Similarly, the invasion of AGS cells was promoted by the S100A10 K47R or K47E mutation according to Transwell assays, with an increased number of cancer cells passing through the Transwell membrane filter in the K47R or K47E S100A10 group." (PMID 30394687, 2019). "We understand that confirming the localization and expression of the S100A10 protein in normal tissues may better reveal the potential role of S100A10 in cancer cells." (PMID 31739800, 2019). "S100A10 plays a role in promoting the migration of cancer cells." (PMID 30572596, 2018). "Several studies have shown that S100A10 plays a role in promoting the invasion of cancer cells." (PMID 30572596, 2018). "Extracellularly, the S100A10/annexin II complex functions as a plasminogen receptor, and regulates the tissue plasminogen activator (tPA)-dependent plasminogen activation and the plasmin formation on cancer cells." (PMID 30558666, 2018). "S100A10 was highly expressed in many cancer cell lines including upper respiratory tract (n = 30; mean = 0.6671 C.I 0.6314–0.7029), pancreatic (n = 44; mean = 0.6657, CI: 0.5948–0.7366), and esophageal (n = 25; mean = 0.6542, CI: 0.5838–0.7245) cancer cell lines." (PMID 30009399, 2018). "S100A10 regulates between 50–90% of the plasmin generation of a number of normal and cancer cells." (PMID 27351226, 2016). "In addition to PLAUR and LAMB3, S100A10 was another gene upregulated by both hypoxia and hypoglycaemia based on our array analysis, and has been shown to be important in cancer cell invasion and metastasis through colocalization with uPA/PLAUR system." (PMID 25079072, 2014). "S100A10 has thus attracted considerable attention for its role in cancer development." (PMID 22206547, 2011). "Interestingly only 27.5% of the cancer tissues stained positive for S100A10." (PMID 34944416, 2021). "In addition, we previously identified S100A10 as a key plasminogen receptor that empowers stromal cells and many cancer cells with the ability to promote plasminogen activation during malignant progression of cancer cells." (PMID 30237490, 2018). "Overexpression of AnxA2 (as is seen in some cancers) or nonstoichiometric changes in the relative concentrations of AnxA2 and S100A10 may have more severe phenotypes than loss of both." (PMID 22505935, 2012). "The present work shows that silencing S100A10 or S100A11 resulted in distinct outcomes in hepatic malignant transformation and cancer progression." (PMID 40841353, 2025). "In order to indicated the role of the family members in HCC development, we further analyzed the expression of S100A4, S100A6, S100A10, S100A11 and S100A16 in pan-cancer, and the results suggested that they were highly expressed in most tumors." (PMID 37420211, 2023).
cancer (continued). "Differential expression analyses comparing cancer areas of rHGP and dHGP revealed established CRC cell markers, such as FABP1, CEACAM5, CLDN3, EPCAM and S100A10 in the rHGP (Supplementary Spreadsheet 1)." (PMID 36691028, 2023). "Compared to S100A10, presently much fewer studies explore the relations between FCER1A, FNTA, and cancer." (PMID 36430822, 2022). "Finally, the mechanisms in the cancer-promoting activity of S100A10 are still unknown." (PMID 34178044, 2021). "The expression of S100A10 was analyzed using the Oncomine database, Gene Expression Profiling Interactive Analysis (GEPIA), The Cancer Genome Atlas (TCGA), and the UALCAN cancer database." (PMID 33324631, 2020). "Regarding its relationship with TB/PDC of CRC, S100A10, and ANX A2 are related not only to poor differentiation but also to the budding of a special type of cancer cells, namely, polyploid giant cancer cells (PGCCs)." (PMID 33160379, 2020). "To assess the relative expression levels of the S100A10 gene in cancer, we examined S100A10 mRNA levels (RNA seq V2 RSEM) across all 33 cancer types in the genomics data commons portal of the National Cancer Institute." (PMID 30009399, 2018). "This study identifies for the first time, the plasminogen receptor, S100A10, as a key link between RAS-dependent oncogenic transformation of cells and RAS-dependent increases in plasmin proteolytic activity and cancer cell invasion." (PMID 27351226, 2016). "Some cancer-related genes are located in these highly common, early appearing RARs: MCL1, CTSK, ARNT, S100A10, PTK2, PTP4A3, and PSCA in the RAR-Gs; and DLC1, PINX1, and GATA4 in the RAR-Ls." (PMID 22938721, 2012). "Most noticeably, abnormal expression of many S100 proteins, such as S100A2, S100A4, S100A6, S100A8, S100A9, S100A10, and S100A11 is found in numerous cancers." (PMID 21897749, 2011). "While abnormal expression of many S100A proteins were found in cancer cells, changes of S100A2 and S100A10 expression were reported in various SCC of the oral cavity, esophagus, the larynx, kidney, and the thyroid." (PMID 21897749, 2011). "In order to elucidate the role of S100A10 in PDAC, the protein expression level of S100A10 was detected in six PDAC cancer cell lines by western blotting, and PANC-1 and AsPC-1 with the relatively high expression level of S100A10 were selected for further study." (PMID 36612197, 2022). "It is thus not surprising that an elevated level of S100A10 is a common feature of many cancers, such as squamous cell carcinoma, colon, lung, breast, or pancreatic cancer." (PMID 34356598, 2021). "Taking into account the increased level of S100A10 and GRHL2 in many cancers, it is possible that regulation of S100A10 expression by GRHL2 might have an impact on cancer progression and metastasis." (PMID 34356598, 2021). "S100A10 and uPAR co-localize at the cell surface bringing together plasminogen and uPA and therefore promoting the generation of the serine protease, plasmin and subsequent degradation of the ECM which is fundamental for cancer cell invasion." (PMID 32867190, 2020). "The interaction between annexin A2, S100A10, and t-PA mediates the conversion of plasminogen to plasmin, which facilitates the ECM degradation, MMP activation, and angiogenesis, leading to increased cancer cell migration, invasion, and metastasis." (PMID 30572596, 2018). "Fourth, when the HCC cases were categorized according to cancer pathological grade, high mRNA expression of S100A7 in pathological grades II and III correlated with shorter OS, as did high expression of S100A9 in pathological grade II and of S100A10 in pathological grade III." (PMID 39128058, 2024). "Further supporting the importance of S100 specific members in cell motility and cancer metastasis, matrix metalloproteinase (MMP) expression/activity and degradation of the extra-cellular matrix (ECM) is also under the control of S100 proteins such as S100A4, S100A8, S100A9, S100A10 and S100A14." (PMID 36232334, 2022).
cancer (continued). "This is unlike other types of cancer in which S100A10 is upregulated." (PMID 34944416, 2021). "Doing a differential expression between the two clusters of cancer fibroblasts, we found metastatic fibroblasts were found to express higher levels of soluble factors compared to primary fibroblasts including, CXCL12, S100A6, S100A10, SFRP2,SFRP4,IGF1, CXCL14, ANGPTL4 and IL6." (PMID 30383866, 2018). "Therefore, S100A10 protein is overexpressed in carcinoma (PDAC) regions compared to PanINs, normal ducts, and nonductal stroma." (PMID 30009399, 2018). "However, the mechanism of S100A10 nuclear localization in malignant tumors has not been reported." (PMID 34336846, 2021).
infection (13 papers, 2012 to 2025). The state of being infected such as from the introduction of a foreign agent such as serum, vaccine, antigenic substance or organism. "We next investigated the effect of infection on astrogliosis by measurement of the expression of complement 3 (C3, a neurotoxic reactive astrocyte marker) and S100A10 (a neuroprotective marker)." (PMID 40420159, 2025). "Taken together, these results indicate that SARS-CoV-2 infection effectively downregulated de novo transcription of both ANXA2 and S100A10 early during infection." (PMID 38913740, 2024). "Using HPV16 pseudovirions (PsVs) containing a GFP reporter plasmid, we then screened at least two S100A10 KO and two A2t KO clones and found consistent inhibition of infection, confirming previously reported findings." (PMID 30076379, 2018). "Upon interaction with host cells, HPV establishes infection by traversing through an endocytic pathway that is clathrin- and caveolin-independent, but dependent on the annexin A2/S100A10 heterotetramer (A2t)." (PMID 30076379, 2018). "Despite previous evidence demonstrating a direct interaction between S100A10 and HPV L224, inhibition of infection in the S100A10 KO was reproducibly less pronounced compared to the full A2t KO for all genotypes tested." (PMID 30076379, 2018). "For gene candidates, Vav3, Ptpn22, FcgR1 and S100a10, qPCR corroborated up-regulated expression found in susceptible AKR on day 35 post infection." (PMID 23442222, 2013). "Taken together, we speculated that the intrauterine transmission of HBV might utilize a similar vesicle transport mechanism to achieve maternal and infant infections through S100A10/AnxA2-mediated exocytosis in placental cells." (PMID 34645932, 2022). "The differences between infection in S100A10 KO versus A2t KO cells could be explained by the fact that S100 family members S100A4, S100A6, and S100A11 are also able to complex with AnxA2 and are expressed in cervical epithelium." (PMID 30076379, 2018). "To ensure that the observed inhibition of infection was specifically due to the S100A10 and AnxA2 gene editing, we restored AnxA2 expression in the A2t KO cells by plasmid transfection which stabilized S100A10 protein expression and thus reintroduced heterotetrameric A2t." (PMID 30076379, 2018). "Dziduszko and Ozbun also showed that both ANXA2 and S100A10 play a role in HPV16 entry and infection by showing that early HPV16 binding results in the translocation of AIIt to the extracellular surface." (PMID 34944495, 2021). "In contrast, the use of the S100A10 antibody in HaCaT cells inhibited infection in the late nucleus, suggesting that ANXA2 and S100A10 may have different roles." (PMID 39057791, 2024). "This may have tuned the local innate immune response to better counteract the infection, while also limiting excessive tissue damage that can exacerbate inflammation, as evidenced by reduced levels of LDH and the DAMP molecule S100A10 in BAL fluid." (PMID 36969366, 2023). "Overall, the observed reduction in infection is less significant in the absence of S100A10 alone compared to full A2t, supporting an independent role for monomeric AnxA2." (PMID 30076379, 2018). "By contrast, S100A10 expression was not significantly changed by either infection." (PMID 40420159, 2025). "First, we demonstrated that ANXA2 mRNA and protein levels increased during the invasion of M. bovis, and S100A10, the interacting protein of ANXA2, was also upregulated in M. bovis infection, indicating ANXA2 might together with S100A10 participate in its infection." (PMID 36159852, 2022). "Moreover, by comparing fluorescence intensity, we found that the expression level of S100A10 and the amount of intracellular virus were not significantly related to the durational length of infection." (PMID 34645932, 2022). "We next asked if the observed decrease in infection could be explained by a reduction in HPV internalization in the absence of S100A10 and A2t." (PMID 30076379, 2018).
cardiovascular disease (2 papers, 2015 to 2025). "However, S100A10, as a member of the S100a family, has been less studied in cardiovascular diseases." (PMID 41195005, 2025). "Second, the interaction between S100A10 and ANXA2 may involve other complex molecular mechanisms that require further exploration and the clinical application of S100A10 and ANXA2 in cardiovascular diseases requires evaluation through larger-scale clinical studies." (PMID 41195005, 2025).
adenocarcinoma (1 paper, 2018). A common cancer characterized by the presence of malignant glandular cells. "We first compared total and surface S100A10 levels between the bronchial epithelial cell line BEAS-2B and the adenocarcinoma cell line A549 cells using flow cytometry." (PMID 30237490, 2018).
S100A10 also shares sentences with these, for which no sentence is quoted: lung adenocarcinoma (4 papers); astrocytoma (3); thyroid cancer (3); meningioma (2); mental disorder (2); mood disorder (2); multiple myeloma (2); prediabetes (2); rheumatoid arthritis (2); sarcoidosis (2); tenosynovial giant cell tumor (2); acute myeloid leukemia (1); Alzheimer disease (1); asthma (1); bacterial infection (1); basal cell carcinoma (1); bipolar disorder (1); cervical cancer (1); colon adenocarcinoma (1); colorectal adenocarcinoma (1); colorectal tumor (1); connective tissue tumors (1); diffuse gastric adenocarcinoma (1); dilated cardiomyopathy (1); dyslipidemia (1); Eczema (1); end-stage renal disease (1); endocervical carcinoma (1); endometrial carcinoma (1); endometrioid ovarian cancer (1).
A further 34 diseases each share a sentence with S100A10 in 1 paper.